CRP (C-reactive protein)
Diseases named in the same sentence as CRP in open-access papers (continued):
Sharing a sentence is not in itself a finding about the gene and the disease.
malaria (continued). "The present study was performed to investigate if polymorphisms in the CRP gene could contribute to the lower susceptibility to malaria seen in the Fulani ethnic group." (PMID 19545442, 2009). "Cote d’Ivoire, Liberia, and Pakistan are all countries where malaria is present, and rural communities tend to have higher parasitemia than in urban communities, which is probably reflected in the association between rural living and elevated CRP and AGP concentrations." (PMID 28615263, 2017). "We assessed baseline C-reactive protein (CRP) and procalcitonin levels in asymptomatic individuals from malaria-endemic West Africa." (PMID 41799261, 2026). "Elevated CRP (>50 mg/L) was significantly more frequent in bacterial and rickettsial infections than in viral illness (malaria, 5 (100%); leptospirosis, 14 (77.8%); scrub typhus, 32 (62.7%) vs. dengue, 8 (16.7%)." (PMID 42093780, 2026). "A recent meta-analysis even proposed the C-reactive protein as an early biomarker for malaria and for monitoring malaria severity." (PMID 40243929, 2025). "We show during malaria age is associated with increased inflammatory chemokines CCL2, CCL3, CXCL8, CXCL9, along with CRP, and IDO, which associate with symptoms." (PMID 41027884, 2025). "Competency and disease knowledge were assessed for 16 VMWs (Malaria/CRP Duo RDT, n = 8; Dengue Duo RDT, n = 8) from five health centre catchment areas (Prey Tralach, Tasanh, Krachab, Koas Kralor, Boeung Run)." (PMID 40340660, 2025). "During this one-year period, a total of 2,425 febrile patients were assessed with a combo-RDT (Dengue Duo, n = 915; Malaria/CRP, n = 1,510)." (PMID 40340660, 2025). "This is likely to be the main reason that fewer Dengue Duo RDTs were performed compared to the Malaria/CRP RDT." (PMID 40340660, 2025). "All six malaria-positive children with chronic inflammation equally had acute inflammation, as their CRP values were above 5 mg/L." (PMID 40277833, 2025). "We performed a prospective, cross-sectional study in Gabon evaluating the STANDARD Malaria/CRP DUO (S-DUO) RDT." (PMID 39177882, 2025). "Practical performance was excellent for the malaria test (100% correct) but less so for the CRP test (63% correct)." (PMID 40340660, 2025). "It highlights the potential for this combo malaria/CRP RDT to also be utilised to assess the severity of malaria infections when the malaria antigen band is positive." (PMID 39177882, 2025). "S-DUO RDT is suitable for malaria detection in moderate-to-high malaria transmission settings such as in Lambaréné; however, a CRP band detection limit > 40 mg/L is more adequate for indication of antibiotic prescription for AFI cases in Gabon." (PMID 39177882, 2025). "Expert microscopy, SD Bioline Malaria Ag P.f/Pan test for malaria detection, and NycoCard CRP device for CRP were used as comparators." (PMID 39177882, 2025). "The present study showed that malaria profoundly impacts immune biomarkers, particularly by increasing the level of inflammation biomarkers like AGP and CRP and decreasing IgG4, a marker associated with immune regulation." (PMID 40277833, 2025). "During the study period, VMWs were required to test patients with the CNMCP-provided malaria RDT simultaneously, with either the Dengue Duo or Malaria/CRP RDT." (PMID 40340660, 2025). "S-DUO RDT sensitivity and specificity for malaria detection vs. microscopy were 99·1% (95·2–100%) and 72·7% (64·3–80·1%); and for CRP detection (20 mg/L and above) 86·9% (80–92%) and 87% (79·2–92·7%), respectively." (PMID 39177882, 2025). "This work aimed at assessing the serum levels of AGP (chronic inflammation) and CRP (acute inflammation) biomarkers and IgG4 and their correlation with malaria in children below five years in the Buea Health District of the South West Region of Cameroon." (PMID 40277833, 2025). "Malaria causes inflammation, and inflammatory biomarkers like α-1-glycoprotein (AGP) and C-reactive protein (CRP) are elevated in serum during malaria." (PMID 40277833, 2025).
malaria (continued). "For instance, in 2024, the costs for a CRP, procalcitonin, and blood culture were approximately $6.67, $10, and $10, respectively, in Jos, as compared to a malaria test, which was $0.67." (PMID 40535411, 2025). "White blood cell count and differential, CRP, and malaria testing were applied systematically across intervention groups in all three countries, whereas the seven other POC tests were applied variably based on patients’ symptoms and test availability." (PMID 39378867, 2024). "In brief, the preliminary results showed that 1511 malaria/CRP RDTs were performed by VMWs, of which 58 (3.8%) were positive (55 positive for raised CRP and three positives for malaria)." (PMID 38166839, 2024). "In high endemicity, inflammation-adjusted ferritin values between malaria groups were very similar at low level of CRP." (PMID 39450524, 2024). "Although not the primary focus of our study, we noted an important finding related to CRP measurement in this malaria-endemic region." (PMID 38241274, 2024). "We analysed venous blood samples for malaria, Hb, ferritin, retinol, folate, Zn, vitamin B12, C-reactive protein, α1-acid glycoprotein (AGP) and β-thalassaemia." (PMID 38185818, 2024). "These included dengue antigen–antibody RDTs, combined malaria/CRP tests, and multiplexed biosensors." (PMID 38166839, 2024). "In Kenya, a country with moderate endemicity, even a low parasitaemia was associated with an elevation in inflammation-adjusted ferritin, which corresponds to what we observed at low levels of CRP in moderate malaria endemicity." (PMID 39450524, 2024). "As a part of the study, workshops and focus group discussions were held at nine health centres to explore the practicalities related to multiplexed biosensors, malaria/CRP, and dengue antigen–antibody tests." (PMID 38166839, 2024). "This suggests that CRP, at a cut-off of 23.8mg/L, performs better than malaria RDTs for excluding malaria in febrile children." (PMID 37478118, 2023). "The highest CRP levels were found in children with mixed bacterial infections and malaria, where all had CRP levels >40mg/L." (PMID 37478118, 2023). "Workshops introduced health workers to the STANDARD(TM) Q Dengue Duo, STANDARD(TM) Q Malaria/CRP Duo and a multiplex biosensor detecting antibodies and/or antigens of eight pathogens." (PMID 37317948, 2023). "Most children with viral monoinfection (106/128) had CRP levels less than 20mg/L, while most children with bacterial monoinfection (30/42) and malaria monoinfection (23/29) had CRP levels greater than 20mg/L." (PMID 37478118, 2023). "A total of five participants performed the Dengue Duo, three for the Malaria/CRP Duo and four each for the DPP Antigen and DPP Antibody groups." (PMID 37317948, 2023). "The optimal cut-off value of CRP was calculated to 36.2mg/L for bacterial infection and 23.6mg/L for malaria." (PMID 37478118, 2023). "It is therefore important to study the relationship between CRP, malaria and bacterial infection in detail so as to determine CRP’s use in differentiating between these conditions, especially in pediatric populations where these two conditions are prevalent." (PMID 37478118, 2023). "In this case, markers such as C-reactive protein (CRP) cannot help since CRP levels are usually increased in the presence of malaria." (PMID 37490737, 2023). "Participants discussed patients’ dissatisfaction with the relatively larger amount of blood required for the dengue test (110 μl for the dengue test compared with 15 μl for the malaria/CRP test, 50 μl for the DPP Antigen and 10 μl for the DPP Antibody)." (PMID 37317948, 2023). "Search terms used included ‘CRP use in febrile patients’, ‘CRP use to predict bacterial infection’ and ‘CRP use to predict malaria’." (PMID 37478118, 2023). "Volunteers (CHWs) would be able to carry out the Dengue Duo and Malaria/CRP Duo, but they would need more training sessions compared with HCWs." (PMID 37317948, 2023).
malaria (continued). "Twenty-five participants were in the Dengue Duo group; 14 in the Malaria/CRP Duo group; 12 in the DPP Antigen group; and 18 in the DPP Antibody group." (PMID 37317948, 2023). "Based on the cut-off CRP values obtained by plotting Youden’s J on the ROC curves, predictive values were calculated for malaria and bacterial infection." (PMID 37478118, 2023). "Positive predictive values (PPV) represent the proportion of true positives among the positive patients, as defined by CRP > 23.6mg/L for malaria and CRP > 36.2mg/L for bacterial infection." (PMID 37478118, 2023). "Burkina Faso had the highest incident rates of malaria and, logically, the highest CRP levels; Ghana had the lowest of both." (PMID 37490743, 2023). "Among the battery of tests provided, malaria test, CRP levels, disease and WBC total and differential counts were applied systematically in the intervention groups in all 3 countries, allowing comparisons across countries." (PMID 37490743, 2023). "CRP can effectively exclude malaria and bacterial infection in febrile children in low-resource settings without the need for additional tests." (PMID 37478118, 2023). "Consenting patients received complete clinical examinations, then venous blood samples were collected and tested for CRP values, bacterial infection and malaria." (PMID 37478118, 2023). "The previous studies indicated the CRP was a prognostic factor and a biomarker for malaria infection and monitoring of malaria severity." (PMID 35619071, 2022). "Concentrations of pan-LDH and CRP were significantly elevated in malaria patients compared to controls for both sample types (P < 0.0001)." (PMID 35508558, 2022). "This presumptive diagnostic will be supported by biomarkers PoC diagnostic tools (CRP, WBC and urine dipstick), pathogen-specific antigen RDT (two step malaria RDT and bacteria), and pulse oximetry to determine if a prescription of antibiotic is needed." (PMID 36109766, 2022). "PCT levels that correlated better with disease severity than CRP were reported in another cohort study that enrolled imported malaria." (PMID 36141662, 2022). "The PoC tests expected to be performed in this study are malaria RDTs (PfHRP2/pLDH), C-reactive protein RDT, white blood cell (WBC) count, urine dipstick, pulse oximeter, group A Streptococcus RDT, RDT for Salmonella, and Shigella for rapid detection in stool." (PMID 36109766, 2022). "We were unable to assess the utility of CRP in predicting severe malaria in our study due to low numbers of severe malaria cases with whole blood samples available (n = 5)." (PMID 35508558, 2022). "Among the Pf-SM biomarkers, five prognostic biomarkers viz CRP, Ang-2, Ang-2/1 ratio, PfHRP2, and platelet count showed good clinical values in malaria severity and CM." (PMID 36036460, 2022). "In contrast, the host-response protein, CRP, was elevated in significantly more malaria cases when using plasma (89.6%) compared to whole blood (80%)." (PMID 35508558, 2022). "Most of the children who were tested RDT positive for malaria also had a CRP positive test (93.4%; 254/272)." (PMID 36536340, 2022). "The most recent systematic review showed that increased CRP levels were a biomarker for malaria infection and monitoring of malaria severity." (PMID 36141662, 2022). "Another limitation of our work is that the current study design did not allow for statistical testing of sensitivity and specificity of the combined malaria and CRP testing." (PMID 36536340, 2022). "Similar findings in Ivory Coast showed that CRP and plasma ferritin were elevated even during afebrile malaria; furthermore, it showed a decrease in ID prevalence although it was months after treatment." (PMID 34575118, 2021). "The greatest difference of median between malaria and dengue infected patients was observed with CRP." (PMID 34565334, 2021). "It has also been found that individuals with greater malaria disease severity had higher levels of CRP, TNFα, and IFNg." (PMID 33731158, 2021).
malaria (continued). "Between the malaria and dengue groups, the highest area under the receiver operating characteristic curve was observed on CRP (0.867, CRP ≥ 26.85 mg/L)." (PMID 34565334, 2021). "Overall, the pooled analysis demonstrated a higher mean CRP level in asymptomatic malaria patients than in healthy controls (p < 0.001, SMD: 2.55, 95% CI: 1.6–3.5, I2: 99.2%, 10 studies)." (PMID 34764364, 2021). "Addition of CRP increases the specificity of detecting malaria due to the inflammatory response secondary to parasite infection." (PMID 34565334, 2021). "In the healthy control subgroup, the results of the individual study demonstrated a higher mean CRP level in patients with uncomplicated malaria than in healthy controls among the four studies." (PMID 34764364, 2021). "On the other hand, in accordance with previous evidence, malaria increased CRP, though to levels that were significantly lower than those found in bacterial infections." (PMID 34574070, 2021). "Further studies with large sample sizes are needed to determine the performance of CRP to help clinicians in highly malaria-endemic areas make appropriate decisions on malaria treatment." (PMID 34764364, 2021). "The medians of platelet counts (PLT) were 102.5, 109.0, and 223.0 × 103/μL, while CRP medians were 67.4, 81.4 and 10.4 mg/L in P. vivax, P. falciparum and control groups respectively (p < 0.001 in Mann–Whitney U tests between malaria and control groups)." (PMID 34565334, 2021). "This study demonstrated CRP levels are a biomarker for the early detection and monitoring of malaria severity." (PMID 34764364, 2021). "The difference in the mean CRP level between patients with uncomplicated and asymptomatic malaria was estimated from four studies." (PMID 34764364, 2021). "In order to accommodate for this, we included the presence of malaria parasites as a covariate in the model in addition to CRP concentration." (PMID 33184647, 2021). "Overall, the pooled analysis of 12 studies demonstrated a higher mean CRP level in uncomplicated malaria than in febrile/healthy controls (p < 0.001, SMD: 2.38, 95% CI: 1.37–3.40, I2: 98.5%, 12 studies)." (PMID 34764364, 2021). "From our current data set, patients with malaria are 15.78 times more likely to present CRP greater than 26.85 mg/L, compared to dengue patients." (PMID 34565334, 2021). "Median CRP values were within the normal ranges in parasitic infections, while they were higher in malaria." (PMID 34574070, 2021). "The results of the individual studies demonstrated a higher mean CRP level in patients with severe malaria than in those with uncomplicated malaria among 10 studies." (PMID 34764364, 2021). "Differences in CRP levels between patients with severe and uncomplicated malaria were estimated after studies with six stars’ quality were excluded." (PMID 34764364, 2021). "The sTfR response was highest at the end of the wet season, a month following the peak values for malaria prevalence, CRP and hepcidin." (PMID 34579679, 2021). "This is sufficient for the PKPD sampling and modelling to determine an optimal dose in children with severe malaria using change in CRP at 72 hours, and microbiological cure (seven-day) alone and with seven-day survival." (PMID 37519413, 2021). "We found that children with afebrile and severe malaria had higher geometric mean CRP levels (4.62mgl-1 and 100.28mgl-1,respectively) compared to levels in those without malaria (1.15mgl-1)." (PMID 33619371, 2021). "Second, the number of studies included in each analysis was limited because some relevant studies were excluded due to incomplete data for CRP level or clinical status of patients with malaria presented in the literature." (PMID 34764364, 2021). "The combination of providing hematology parameters plus CRP values in a hematology analyzer makes a preferred method for screening malaria on a routine basis in cases of any infection suspicion." (PMID 34565334, 2021).
malaria (continued). "Procedures for extraction of malaria analytes and CRP from DBS samples were optimized by utilizing the calibrator diluent solution included in the 5-Plex kit." (PMID 34290484, 2021). "Laboratory tests were requested for 67.39% of total cases, and the most common test was full blood count (43.48%) followed by C-reactive protein (40.58%) and thick blood smear for malaria microscopy (40.58%)." (PMID 33845920, 2021). "A pooled analysis using the fixed-effects model demonstrated a higher mean CRP level in patients with uncomplicated malaria than in those with asymptomatic malaria (p < 0.001, SMD: 1.52, 95% CI: 1.36–1.69, I2: 96.7%)." (PMID 34764364, 2021). "Subgroup analysis of types of infection demonstrated a higher mean CRP level in patients with severe malaria than in uncomplicated malaria patients in studies of patients with P. falciparum (p < 0.001, SMD: 1.19, 95% CI: 0.57–1.82, I2: 94.06%, seven studies)." (PMID 34764364, 2021). "A pooled analysis using the fixed-effects model demonstrated a higher mean CRP level in patients with severe malaria than in those with uncomplicated malaria (p < 0.001, SMD: 0.93, 95% CI: 0.81–1.06, I2: 95.1%)." (PMID 34764364, 2021). "Results demonstrated a higher mean CRP level in patients with severe malaria than in those with uncomplicated malaria (p: 0.006, SMD: 1.21, 95% CI: 0.35–2.06, I2: 96%, six studies)." (PMID 34764364, 2021). "Subgroup analysis of types of infection demonstrated a higher mean CRP level in patients with asymptomatic malaria than in febrile/healthy controls in studies of patients with P. falciparum (p < 0.001, SMD: 3.39, 95% CI: 1.93–4.85, I2: 99.2%, seven studies)." (PMID 34764364, 2021). "We previously reported that the increased levels of CRP, an acute phase inflammatory protein are found in febrile malaria cases." (PMID 34290484, 2021). "The difference in the mean CRP level between patients with uncomplicated malaria and febrile/healthy controls was estimated from 12 studies." (PMID 34764364, 2021). "The LC-667G CRP, a three-part differential hematology analyzer has the potential to not only trigger malaria diagnosis confirmation, but also to assess the severity of the infection due to simultaneous CRP estimations." (PMID 34565334, 2021). "The pooled analysis in these subgroups demonstrated a higher mean CRP level in patients with uncomplicated malaria than in febrile controls (p: 0.028, SMD: 1.80, 95% CI: 0.19–3.4, I2: 98.9%, 6 studies)." (PMID 34764364, 2021). "The pooled analysis in these subgroups demonstrated a higher mean CRP level in patients with uncomplicated malaria than in healthy controls (p < 0.001, SMD: 3.80, 95% CI: 2.78–4.83, I2: 86%, 4 studies)." (PMID 34764364, 2021). "Most participants with positive CRP or IMS result were malaria microscopy positive, supporting the confounding effect of malaria on CRP or IMS results." (PMID 33647009, 2021). "The pooled analysis of 11 studies showed a higher mean CRP level in patients with severe malaria than in those with uncomplicated malaria (p < 0.001, SMD: 1.52, 95% CI: 0.91–2.12, I2: 95.1%)." (PMID 34764364, 2021). "The difference in the mean CRP level between patients with severe and uncomplicated malaria was estimated from 11 studies." (PMID 34764364, 2021). "Differences in CRP levels between patients with severe and uncomplicated malaria were estimated after studies reporting the mean CRP were excluded." (PMID 34764364, 2021). "The pooled analysis of the four studies showed a higher mean CRP level in patients with uncomplicated malaria than in those with asymptomatic malaria (p < 0.001, SMD: 1.65, 95% CI: 0.67–2.62, I2: 96.7%, 4 studies)." (PMID 34764364, 2021). "When using CRP level as a marker of malaria severity, a previous study showed that a cut-off value for CRP level of 18.5 mg/L discriminated severe malaria from uncomplicated malaria with 71.4% sensitivity and 68.7% specificity." (PMID 34764364, 2021).